MIR153-2 (microRNA 153-2)
Synonyms: hsa-mir-153-2; MIRN153-2; mir-153-2
Gene: MicroRNA gene on chromosome 7 (157,574,336 to 157,574,422, reverse strand). Ensembl gene ENSG00000207960.
Gene Ontology:
Cellular component: RISC complex
Homologues: Orthologues: chimpanzee ptr-mir-153 (100% identical), macaque mml-mir-153-2 (100% identical), pig ssc-mir-153 (100% identical), rabbit MIR153-2 (100% identical), rat Mir153 (100% identical), tropical clawed frog xtr-mir-153-2 (94% identical), dog MIR153-2 (92% identical), zebrafish dre-mir-153a (91% identical), guinea pig MIR153-2 (79% identical). Paralogues in human: MIR153-1 (78% identical).